DYNLL1 (dynein light chain LC8-type 1)
Description:
Component of dynein, a family of motor proteins essential for movement along microtubules (By similarity). Required for structural and functional integrity of cilia (By similarity). Acts as one of several non-catalytic accessory components of the cytoplasmic dynein 1 complex that are thought to be involved in linking dynein to cargos and to adapter proteins that regulate dynein function (By similarity). Cytoplasmic dynein 1 acts as a motor for the intracellular retrograde motility of vesicles and organelles along microtubules (By similarity). May play a role in changing or maintaining the spatial distribution of cytoskeletal structures (By similarity). In addition to its role in cytoskeleton and transport, acts as a protein-protein adapter, which inhibits and/or sequesters target proteins. Involved in the response to DNA damage by acting as a key regulator of DNA end resection: when phosphorylated at Ser-88, recruited to DNA double-strand breaks (DSBs) by TP53BP1 and acts by disrupting MRE11 dimerization, thereby inhibiting DNA end resection. In a subset of DSBs, DYNLL1 remains unphosphorylated and promotes the recruitment of the Shieldin complex. Binds and inhibits the catalytic activity of neuronal nitric oxide synthase/NOS1 (By similarity). Promotes transactivation functions of ESR1 and plays a role in the nuclear localization of ESR1. Regulates apoptotic activities of BCL2L11 by sequestering it to microtubules. Upon apoptotic stimuli the BCL2L11-DYNLL1 complex dissociates from cytoplasmic dynein and translocates to mitochondria and sequesters BCL2 thus neutralizing its antiapoptotic activity.
Synonyms: DLC8; PIN; DLC1; DNCL1; DNCLC1; HDLC1; LC8; LC8a
Tractability: Small molecule: a structure with a bound ligand is known. Antibody: its Gene Ontology location is reachable by antibodies, with high confidence. PROTAC: UniProt records ubiquitination sites on it; ubiquitination databases record sites on it; its protein half-life has been measured.
Gene: Protein-coding gene on chromosome 12 (120,469,804 to 120,498,495, forward strand). Ensembl gene ENSG00000088986.
Subcellular location: Cytoplasm, cytoskeleton, microtubule organizing center, centrosome; Chromosome; Cytoplasm, cytoskeleton; Nucleus; Mitochondrion
Subcellular location (Human Protein Atlas): Cytosol; Mid piece; Nucleoplasm; Principal piece
Pathways (Reactome):
Cell Cycle: AURKA Activation by TPX2; Amplification of signal from unattached kinetochores via a MAD2 inhibitory signal; EML4 and NUDC in mitotic spindle formation; Loss of Nlp from mitotic centrosomes; Loss of proteins required for interphase microtubule organization from the centrosome; Mitotic Prometaphase; Recruitment of NuMA to mitotic centrosomes; Recruitment of mitotic centrosome proteins and complexes; Regulation of PLK1 Activity at G2/M Transition; Resolution of Sister Chromatid Cohesion; Separation of Sister Chromatids
Autophagy: Aggrephagy; Macroautophagy
Immune System: MHC class II antigen presentation; Neutrophil degranulation
Organelle biogenesis and maintenance: Anchoring of the basal body to the plasma membrane; Intraflagellar transport
Vesicle-mediated transport: COPI-independent Golgi-to-ER retrograde traffic; COPI-mediated anterograde transport
Cellular responses to stimuli: HSP90 chaperone cycle for steroid hormone receptors (SHR) in the presence of ligand
Disease: HCMV Early Events
Programmed Cell Death: Activation of BIM and translocation to mitochondria
Signal Transduction: RHO GTPases Activate Formins
Gene Ontology:
Molecular function: enzyme inhibitor activity; protein binding; dynein intermediate chain binding; enzyme binding; identical protein binding; nitric-oxide synthase inhibitor activity; nitric-oxide synthase regulator activity; protein domain specific binding; protein-containing complex binding; scaffold protein binding
Biological process: negative regulation of DNA strand resection involved in replication fork processing; negative regulation of phosphorylation; substantia nigra development; intraciliary retrograde transport; motile cilium assembly; positive regulation of intracellular transport; positive regulation of mitotic cell cycle spindle assembly checkpoint; microtubule-based process; positive regulation of insulin secretion involved in cellular response to glucose stimulus; spermatid development
Cellular component: centrosome; chromosome; COP9 signalosome; cytoplasm; cytoplasmic dynein complex; cytoskeleton; kinetochore; membrane; mitochondrion; mitotic spindle; nucleoplasm; nucleus; site of double-strand break; ciliary tip; cilium; cytosol; dynein complex; ficolin-1-rich granule membrane; male germ cell nucleus; plasma membrane; tertiary granule membrane; axon cytoplasm; microtubule associated complex; microtubule cytoskeleton; secretory granule
Genetic constraint (gnomAD): Loss-of-function variants: 3 observed, 10.42 expected, observed/expected ratio (o/e) 0.29, 90% interval 0.13 to 0.74. The upper end of that interval is the gene's LOEUF score, 0.74, which puts it in group 3 of 6, group 1 being the genes least tolerant of losing a copy. Missense variants: 47 observed, 115.16 expected, observed/expected ratio (o/e) 0.41, 90% interval 0.32 to 0.52. Synonymous variants: 46 observed, 41.7 expected, observed/expected ratio (o/e) 1.1, 90% interval 0.87 to 1.41.
Homologues: Orthologues: chimpanzee DYNLL1 (100% identical), guinea pig DYNLL1 (100% identical), macaque DYNLL1 (100% identical), mouse Dynll1 (100% identical), pig DYNLL1 (100% identical), rabbit DYNLL1 (100% identical), rat Dynll1 (100% identical), zebrafish dynll1 (97% identical), Drosophila melanogaster Cdlc2 (94% identical), Drosophila melanogaster ctp (94% identical), tropical clawed frog dynll1 (93% identical), Caenorhabditis elegans dlc-1 (92% identical). Paralogues in human: DYNLL2 (93% identical).
Diseases named in the same sentence as DYNLL1 in open-access papers:
DYNLL1 is named in the same sentence as 43 diseases in open-access papers, as found by Europe PMC text mining. Sharing a sentence is not in itself a finding about the gene and the disease. The quoted sentences say what the papers report.
breast cancer (7 papers, 2009 to 2022). A primary or metastatic malignant neoplasm involving the breast. "In breast cancer, overexpression of DYNLL1 protects cells from UV-induced apoptosis and promotes cancerous properties." (PMID 35619131, 2022).
B-cell lymphoma (4 papers, 2017 to 2022). "DYNLL1 is reported to be a critical regulator of B cell development and its overexpression is linked to Myc-driven B-cell lymphoma in a mouse model." (PMID 31448224, 2019). "In addition, recent reports indicate that ATMIN and Dynll1 are involved in the development of B cell lymphoma, providing a link between dysregulated B cell development, BCMA, and ATMIN signaling in MM." (PMID 35881112, 2022). "Moreover, the loss of DYNLL1 dramatically delays the development and expansion of MYC-driven B-cell lymphoma in mice due to increased BIM-mediated apoptotic cell death, although BIM levels are not elevated." (PMID 35619131, 2022).
ovarian carcinoma (3 papers, 2021 to 2025). A malignant neoplasm originating from the surface ovarian epithelium. "In ovarian cancer, ATMIN promotes cisplatin resistance by regulating the DYNLL1-MRN signaling axis; in tongue cancer, ATMIN promotes tumor metastasis by activating KRAS pathway, while its role in NPC remains to be investigated." (PMID 38321024, 2024).
viral infection (3 papers, 2013 to 2025). "Thus, our study opens a revolutionary area of research by addressing the role of DYNLL1 in bacterial infections other than viral infections." (PMID 24098557, 2013). "We speculate that binding of DYNLL1 to Pilin may trigger an uncontrolled inflammatory response of the host immune system during P. aeruginosa chronic infections thereby opening a new pioneering area to investigate the role of DYNLL1 in gram negative bacterial infections other than viral infections." (PMID 24098557, 2013).
cardiac hypertrophy (2 papers, 2021 to 2023). "A total of six hub genes (TANC2, ADAMTS2, DYNLL1, MRC2, EGR1, and OTUD1) were considered cardiac hypertrophy and HF regulators." (PMID 37498303, 2023). "Six hub genes (TANC2, ADAMTS2, DYNLL1, MRC2, EGR1, and OTUD1) showed anomaly trend in cardiac hypertrophy." (PMID 37498303, 2023).
hepatocellular carcinoma (2 papers, 2021 to 2022). A malignant tumor that arises from hepatocytes. "For instance, DYNLL1 alternative splicing expression, which is significantly decreased in EGCG+HC treated glioma cells, is reported to be upregulated in gastric cancer high-risk group patients and hepatocellular cancer." (PMID 35392560, 2022).
Alzheimer disease (1 paper, 2021). A progressive, neurodegenerative disease characterized by loss of function and death of nerve cells in several areas of the brain leading to loss of cognitive function such as memory and language. "Previous studies have demonstrated the major role of altered DYNLL1 protein in dementia, Alzheimer’s disease, aging, and other neuropsychiatric processes." (PMID 34827437, 2021).
COVID-19 (1 paper, 2023). A disease caused by infection with severe acute respiratory syndrome coronavirus 2. "In contrast, downregulation of genes encoding HLA class 2 (HLA-DRA, HLA-DPA1, HLA-DMA, DYNLL1) was found in COVID-19 ECs which was further confirmed by GSEA analysis." (PMID 37029220, 2023).
diabetic nephropathy (1 paper, 2025). "In diabetic nephropathy, nephrin is internalized inside endocytic vesicles mediated by dynein light chain 1 (DYNLL1), and eventually, nephrin is degraded in the lysosome." (PMID 40072092, 2025).
dilated cardiomyopathy (1 paper, 2023). Cardiomyopathy which is characterized by dilation and contractile dysfunction of the left and right ventricles. "In another bioinformatics study, DYNLL1 was also upregulated in dilated cardiomyopathy." (PMID 37498303, 2023).
Huntington disease (1 paper, 2022). Huntington disease (HD) is a rare neurodegenerative disorder of the central nervous system characterized by unwanted choreatic movements, behavioral and psychiatric disturbances and dementia. "The DYNLL1 and KLRN genes may be involved with AD and Huntington’s disease (HD) phenotypes and represent a common genetic basis of these diseases." (PMID 35327413, 2022).
Listeria infection (1 paper, 2020). "To gain more insight into the potential role of Dynll1 during Listeria infection, we screened for its interacting partners using immunoprecipitation (IP)-MS studies." (PMID 32041786, 2020). "The Dynll1-Cox4i1 complex itself also may have other mechanisms to combat Listeria infection, as reflected in our data." (PMID 32041786, 2020).
lymphopenia (1 paper, 2017). Reduction in the number of lymphocytes. "Consistent with this notion, the SWHEL BCR, or just its (homozygous) VH10 heavy chain knock-in, led to a ~5-fold reduction of B-1a cells compared to control mice, and thereby further compounded the B-1a lymphopenia in Dynll1-deleted mice." (PMID 28922373, 2017). "This differential effect of the SWHEL transgene, which even worsened the B-1a lymphopenia in Dynll1-deleted mice, is best explained by the concept that B-1a and B-2 cells have distinctive Ig repertoires." (PMID 28922373, 2017). "In fact, in both Asciz or Dynll1 mutant mice, there was a trend towards a modest rescue of the B-1a lymphopenia by Eμ-Myc, possibly reflecting increased MYC-driven self-renewal of the B-1a cell pool." (PMID 28922373, 2017).
melanoma (1 paper, 2022). A malignant, usually aggressive tumor composed of atypical, neoplastic melanocytes. "Nevertheless, RNAi against DYNLL1 leads to reduced Bim levels to varying degrees in HeLa epithelial cells and 1205Lu melanoma cells." (PMID 35619131, 2022).
periodontal disease (1 paper, 2022). "As shown in the boxplot, the expression of CD14, FCGR1A, DYNLL1, and FCGR2B correlated with disease status; therefore, these data suggest that these key genes may be important targets for the treatment of periodontal disease." (PMID 36212719, 2022).
serous ovarian cancer (1 paper, 2022). "Although the exact relationship between DYNLL1 and the 53BP1 axis is still unclear, loss of DYNLL1 was associated with PARPi resistance in a panel of patient-derived BRCA1-mutant high-grade serous ovarian cancer lines." (PMID 35681784, 2022).
cancer (12 papers, 2007 to 2025). A tumor composed of atypical neoplastic, often pleomorphic cells that invade other tissues. "How DYNLL1 promotes aberrant transcription in cancers are still unknown." (PMID 35392560, 2022). "Finally, DHHC9's broader oncogenic roles, including immune modulation via PD‐L1 or other substrates (e.g., STK3, DYNLL1), were not explored, leaving gaps in understanding its multifaceted contributions to cancer progression." (PMID 40903842, 2025). "In addition, siRNA-mediated silencing of all transcripts of eight genes that showed a consistent differential splicing signature across multiple cancer types (ABCC5, ANKHD1, DYNLL1, F8, RPL31, TMEM14C, UQCC, and CRNDE) failed to reveal differences in cell viability." (PMID 25424858, 2015).
tumor (11 papers, 2007 to 2025). "In BRCA1-deficient tumor cells, DYNLL1 promotes 53BP1 oligomerization to stimulate NHEJ, and through its interaction with MRE11 Inhibition of DNA end excision, the combination of these two effects leads to genomic instability." (PMID 36091750, 2022). "Likewise, DAP3 and DYNLL1 (apoptosis and cytoskeletal regulators) were overexpressed, underscoring the survival and migration advantages conferred to tumor cells." (PMID 41228302, 2025). "Cellular experiments demonstrated that up-regulation of DYNLL1 expression could reverse the resistance of tumor cells to olaparib." (PMID 36091750, 2022). "This study highlights an entirely novel link between ATMIN regulation of DYNLL1 and tumor hypoxia." (PMID 26875667, 2016).
infection (3 papers, 2013 to 2021). The state of being infected such as from the introduction of a foreign agent such as serum, vaccine, antigenic substance or organism. "In order to further verify the loss of Dynll1 from mitochondria following infection, we extracted mitochondria for Western blot analysis, and the results showed that the extent of Dynll1 was significantly reduced by infection." (PMID 32041786, 2020). "Intriguingly, our data predicted that the types of proteins that interacted with Dynll1 were significantly altered by infection." (PMID 32041786, 2020). "Among them, the expression of Dynll1 in MP increased upon infection was the most significant of the four autophagy-related proteins." (PMID 32041786, 2020). "We found that the interaction between Dynll1 and the mitochondrial respiratory chain member Cox4i1 was significantly lowered after infection." (PMID 32041786, 2020). "Forward and reverse coimmunoprecipitation (Co-IP) assays confirmed that Dynll1 and Cox4i1 could interact and that the extent of the interaction was reduced by infection." (PMID 32041786, 2020). "Our model devised an excellent “infection hypothesis” by assessing a novel role of DYNLL1 in P. aeruginosa pathogenesis, and emphasized the need to further investigate the role of DYNLL1 during bacterial virulence." (PMID 24098557, 2013). "Thus as a fair assessment, major alterations in DYNLL1 cellular distribution and binding perturbations might be coupled dynamically to the subtle regulatory mechanisms during infections." (PMID 24098557, 2013). "In addition, other autophagy-related proteins—Atg2b, Atg4b, and Dynll1—also showed similar expression patterns, suggesting that membrane recruitment of proteins to the autophagosome may be important for the DC response to infection." (PMID 32041786, 2020). "While we were able to identify protein spots for each complex, Rab1a-Dynll1, Snx2-Dynll1, and Canx-Dynll1 were not measurably altered by infection." (PMID 32041786, 2020). "To test whether Dynll1 exercised its functions through interaction with Cox4i1, we generated Cox4i1 knockout and overexpression DC2.4 cell lines and assessed the functional significance of Cox4i1 during infection." (PMID 32041786, 2020). "In this study, we reported a novel infection model for gram negative bacteria PAO (a strain of Pseudomonas aeruginosa) based on a direct interaction of Fimbrial protein Pilin and DYNLL1." (PMID 24098557, 2013).
DYNLL1 also shares sentences with these, for which no sentence is quoted: Hypertension (2 papers); Salmonella Infections (2); uveal melanoma (2); acute myeloid leukemia (1); amyotrophic lateral sclerosis (1); chronic lymphocytic leukemia (1); ciliopathy (1); dementia (1); diabetes (1); escherichia coli infection (1); esophageal squamous cell carcinoma (1); gastric cancer (1); glioma (1); gram-negative bacterial infections (1); Hyperglycemia (1); invasive breast carcinoma (1); lung carcinoma (1); lung chronic infection (1); lymphoma (1); myocardial infarction (1); papillary carcinomas of the breast (1); periodontitis (1); schizophrenia (1); tongue cancer (1).